IL6 (interleukin 6)
Diseases named in the same sentence as IL6 in open-access papers (continued):
Sharing a sentence is not in itself a finding about the gene and the disease.
Sepsis (continued). "The serum levels of IL-1β, IL-6, TNF-α, and IFN-γ levels were increased in the acute phase of sepsis (one day after the surgery, CLP group) as compared with sham mice, suggesting an enhanced systemic inflammatory reaction." (PMID 36148090, 2022). "Conversely, B1a cells also produce IL-3, IL-6, IL-17, and TNF-α, which play proinflammatory roles in sepsis." (PMID 36425582, 2022). "lncRNA CRNDE was upregulated in patients with sepsis and SA-AKI models, and CRNDE overexpression markedly boosted inflammatory cytokine levels, including TNF-α, IL-6, IL-8, and IL-1β." (PMID 35464083, 2022). "Clinical samples of patients with sepsis can have highly elevated levels of TNF-α and IL-6 within one day of diagnosis." (PMID 35167625, 2022). "IL-2R, IL-6, IL-8, IL-10, CCL-2, ICAM-1, and Urokinase were significantly higher in sepsis patients than SIRS patients." (PMID 35363162, 2022). "Clinical and experimental studies have shown that the massive release of proinflammatory cytokines (IL-6 and TNF-α) can trigger sepsis-induced cardiac dysfunction, and inhibition of the expressions of IL-6 and TNF-α can significantly attenuate SIMI." (PMID 35571240, 2022). "B cells can produce a large number of pro-inflammatory cytokines such as IL-3, IL-6, GM-CSF, and TNF-α to enhance the systemic inflammatory responses in sepsis." (PMID 36425582, 2022). "Nicotine (17.5 ± 2 mg/kg, 7 ± 0.8 mg/kg, s.c.)pretreatment reduced the mortality during the early phase of sepsis and reduced the concentrations of TNF-α, IL-1β, IL-6, and MIP-2 after 2 or 10 h of sepsis." (PMID 35251010, 2022). "Post-sepsis platelet transfusions also reduced plasma levels of TNF-α and IL-6 and the organ injury biomarker aspartate aminotransferase (AST)." (PMID 35192546, 2022). "After the sepsis model was established using the CLP method, the serum contents of CORT, IL-6, TNF-α, CRP, and sICAM-1 in the model group were substantially increased compared to those of the control group." (PMID 36338128, 2022). "IL-10 showed positive correlations with the other six cytokines studied in patients with sepsis, and with IL-1β, TNF-α, IL-6, and IL-8 in patients with septic shock." (PMID 36536294, 2022). "Beyond procalcitonin, other frequently studied biomarkers such as CRP, IL-6, IL-8, IL-10, and TNF-α have had much less success predicting infection and sepsis." (PMID 39604183, 2022). "In a pediatric study (n = 60/55 healthy and sepsis patients), miR-146a is decreased in blood and negatively correlated with the levels of C-reactive protein, procalcitonin (PCT), IL-6 and TNF." (PMID 35990654, 2022). "Immunohistochemical (IHC) analysis of paraffin-embedded lungs illustrated that the levels of IL-6 and TNF-α were considerably greater in the sepsis group than in the sham group." (PMID 36685507, 2022). "In the initial stage of sepsis, increased inflammatory cytokines (TNF-α, IL-6, and IL-1β) lead to an inflammatory cytokine storm, which is a main cause of death in this stage." (PMID 35706715, 2022). "Nevertheless, the protein levels of IL-6 and TNF-α reported in included human in vivo studies were still in the value ranges of clinical samples of patients with sepsis or septic shock." (PMID 35167625, 2022). "Like MAMP, AGEs can directly activate the TLR2/4 signaling pathway in various cells and stimulate the production of proinflammatory cytokines such as IL-6 and TNF-α to take part in the pathogenesis of sepsis." (PMID 35719361, 2022). "Levels of IL-6 and TNF-α have been widely assessed in clinical samples under various sepsis conditions and were correlated to disease severity." (PMID 35167625, 2022). "In the CLP animal model, the severity of sickness behavior correlated with sepsis severity, mortality, increased permeability of the BBB, high level of IL-6 and oxidative stress, as well as cognitive and memory impairments." (PMID 35488237, 2022).
Sepsis (continued). "Our data suggested that the relative mRNA levels and protein levels of inflammatory factors (IL-6 and TNF-a) extracted from three organs—the lung, liver, and kidney—were considerably greater in the sepsis group than in the sham group." (PMID 36685507, 2022). "The cytokine levels of IL-2R, IL-6, IL-8, IL-10, and MCP-1 were significantly increased in sepsis patients compared with SIRS patients." (PMID 35363162, 2022). "FTB, DNase1, FTB + DNase1, Cl-amidine, and FTB + Cl-amidine treatment lowered the levels of CRP, IL-6, IL-1β, and TNF-α in rats with sepsis." (PMID 36408247, 2022). "In this study, our results showed that the levels of IL-1β and IL-6 in the lung were increased by LPS treatment and this was significantly inhibited by terrein treatment, suggesting that terrein might be a therapeutic candidate for the treatment of acute lung injury induced by sepsis." (PMID 36422559, 2022). "We chose three proteins as candidate biomarkers, IL-3, IL-6, and PCT, that are known to be elevated in sepsis." (PMID 36129990, 2022). "Infection with influenza A virus induces the production of IL-6 and MIP-1α, which are involved in development of sepsis and induction of the cytokine storm in the lung." (PMID 36614125, 2022). "Compared with those in the sham group, the levels of IL-6, IL-1β and TNF-α in the sepsis group were increased (P < 0.05), the MDA content was increased, and the SOD and CAT activities were decreased (P < 0.05)." (PMID 35576220, 2022). "We found that IL-6, IL-10 and TNF-α levels of the ZM241385-treated sepsis group were decreased in the blood and peritoneal cavity." (PMID 36148230, 2022). "Simultaneously, inflammatory cytokines such as IL-1β and IL-6 activate microglia through the damaged BBB, leading to brain cell destruction and even apoptosis during sepsis." (PMID 35958583, 2022). "Sepsis is a systemic inflammatory response syndrome, often accompanied by the release of a large number of inflammatory cytokines, such as TNF-α and IL-6, in the central and peripheral nervous systems." (PMID 35571246, 2022). "The cytokines production leads to cascades of effects in the onset of sepsis, including pro-inflammatory factors such as TNF-α, IL-1β, and IL-6." (PMID 35510354, 2022). "CRP, combined with sFAS showed increased sensitivity in predicting sepsis than CRP alone, and CRP, PCT, IL-6, sFAS and sVCAM-1 combined had the highest AUC compared to other biomarker combination models." (PMID 35550043, 2022). "Here, we observed that sepsis inhibits PGC–1α expressions in skeletal muscles, whereas IL-6 KO reversed the expression levels of PGC–1α." (PMID 35528525, 2022). "In recent years, more novel sepsis biomarkers, such as HMGB-1, CD64, IL-6, heparin-binding protein (HBP) and triggering receptors expressed on myeloid cells-1 (TREM-1), have been identified." (PMID 36411279, 2022). "The early phase of sepsis is characterized by excessive inflammation with the manifestation of systemically boosted production of pro-inflammatory cytokines, including TNF-α, IL-6 and IL-1β." (PMID 33842398, 2021). "The parameters commonly used to monitor inflammation process and sepsis evolution are lactate, C-reactive protein, procalcitonin, and, more recently, TNF, IL-1beta, and IL-6." (PMID 33685484, 2021). "Among 167 sepsis patients, there was a strong positive correlation between HBP and MPO (r = 0.737, P < 0.001) as well as between IL-6 and IL-8 (r = 0.811, P < 0.001) on admission." (PMID 33461369, 2021). "IL-6, NT-proBNP, and INR provided the best individual performance in predicting 28-day mortality of patients with sepsis or septic shock." (PMID 33446739, 2021). "Cecal ligation and puncture (CLP)-induced sepsis in obese mice results in increased expression of pro-inflammatory cytokines (TNF-α and IL-6) in visceral WAT and decreased circulating adiponectin levels." (PMID 34322037, 2021).
Sepsis (continued). "It was found that the expressions of TNF-α, IL-1β, IL-6 in CLP group were significantly increased (P < 0.001), suggesting that animal’s inflammatory response was activated by sepsis." (PMID 34565302, 2021). "The levels of sIL-2R in the sepsis group were positively correlated with WBC, CRP, SAA, IL-6, and APACHE II (r = 0.387, p = 0.001; r = 0.248, p = 0.038; r = 0.402, p = 0.001; r = 0.532, p < 0.001; and r = 0.244, p = 0.042, respectively)." (PMID 34745113, 2021). "Multiple studies have shown that the levels of inflammation-related factors in serum are directly proportional to the severity of sepsis, such as TNF-α, IL-6, and IL-1β." (PMID 33710444, 2021). "Previous studies have reported that the levels of cytokines such as IL-1, IL-6, IFN-γ, and TNF-α increase during sepsis as an immune response to infection." (PMID 34070883, 2021). "Moreover, transfection of miR-30c-5p mimic had the potential ability to suppress on the level of TNF-α and IL-6 in vivo and presented a protecting effect on the kidney against sepsis-induced injury, indicating that miR-30c-5p could be a novel target for SAKI therapy." (PMID 32892306, 2021). "We previously found that SPIONs significantly improved the symptoms of sepsis and liver injury, which was manifested by decreased levels of AST and ALT, decreased TNF-a and IL-6 levels, and increased IL-10 expression." (PMID 34627385, 2021). "The cytokines IL-1β, IL-6, and TNF-α mediate the immunopathological features of sepsis and are released by neutrophils to exacerbate acute inflammation." (PMID 33588861, 2021). "Multiple biomarkers have been used as diagnostic and/or prognostic biomarkers predicting outcomes for patients with infection/sepsis, including lactate, CRP, cluster of differentiation 64, proadrenomedullin, interleukin-6, procalcitonin, and many others." (PMID 34439240, 2021). "Its derivative, protocatechuic acid isopropyl ester, had been proved to protect murine model against sepsis by inhibiting TNF-α production, NO production, and the augmentation of IL-6 and IL-10." (PMID 34938184, 2021). "IL-6 was measured by the plasmonic-based mobile biosensor and the LFA-AuNPs immunoassay to detect sepsis and visceral leishmania, respectively." (PMID 34372196, 2021). "AKI in sepsis is accompanied by systemic inflammation and the excessive production of pro-inflammatory cytokines including TNF-α, IL-6, and IL-1β." (PMID 33841147, 2021). "The results showed that the levels of the pro-inflammatory cytokines IL-6 and IL-8 and several chemokines (CXCL-8, keratinocyte-derived chemokine, and CCL2), and high-mobility group box-1 (HMGB-1) were higher in dogs with sepsis than in the healthy controls." (PMID 33718468, 2021). "For example, in cecal-ligation and puncture (CLP)-induced sepsis mice, deletion of TLR4 or TLR2 resulted in significantly decreased levels of pro-inflammatory cytokines (i.e., IL-1β, TNF-α, IL-6, and IL-8) and preserved tissue damages." (PMID 34884813, 2021). "High chloride fluids have also been shown in experimental sepsis models to increase TNF, IL-10, and IL-6 concentrations and to impair microcirculatory function compared to balanced crystalloids." (PMID 33718468, 2021). "LPS is a known stimulator in the systemic inflammatory mechanism of sepsis, LPS-triggered ROS generation, and the release of inflammatory cytokines, such as IL-1β, TNF-α, IL-6, and IL-10." (PMID 33986684, 2021). "Accumulating studies have well documented that macrophages play an important role in sepsis as it is one of the major sources of tumor necrosis factor-a (TNF-a) and interleukin-6 (IL-6)." (PMID 33536546, 2021). "To further explore the proinflammatory effects of MSN in sepsis, we next performed ELISA to measure the effects of MSN silencing on the production of the inflammatory cytokines TNF-α, IL-6, IL-1β, and IL-18 in medium supernatant of HMECs." (PMID 33628853, 2021).
Sepsis (continued). "Some studies have demonstrated the usefulness of the circulating IL-6 measurement after traumatic injuries to predict MODS, sepsis, and mortality." (PMID 34073768, 2021). "Biomarkers associated with the innate immune system, especially soluble biomarkers such as cytokines IL-6 and IL-10, CRP, and procalcitonin have shown variable ability to identify hyper inflammation and/or sepsis." (PMID 34065206, 2021). "Berberine inhibits the expression of TNF-α, IL-6, TLR 4, and TLR 9 in the early phase of sepsis in rats." (PMID 34630083, 2021). "The mechanism of sepsis-induced hypocalcemia remains unknown; however, this appears to be associated with elevated levels of proinflammatory cytokines, such as tumor necrosis factor (TNF)-α, interleukin (IL)-1, IL-6; hypoparathyroidism, vitamin D deficiency, or resistance." (PMID 34680835, 2021). "The panel that included C10:2, IL-6, NLR, and C5 discriminated mild patients from sepsis patients with an AUC (95%CI) of 0.965 (0.952–0.977), with sensitivity of 0.993(0.984–1.000) and specificity of 0.851 (0.815–0.887)." (PMID 34460840, 2021). "It was found that sepsis-induced myocardial injury significantly promoted the release of TNF-α, IL-6, and IL-8 and decreased the IL-10 level, compared with that in the sham group." (PMID 33819192, 2021). "The activation of NF-κB participates in the occurrence and development of sepsis by enhancing the transcription of various proinflammatory cytokines, including TNF-α, IL-6, and IL-1β." (PMID 34721636, 2021). "The protein and mRNA expressions of IL-1β, IL-6, and TNF-α were all markedly elevated in renal tissue of mice with CLP-induced sepsis, which were consistent with findings from other studies." (PMID 34187277, 2021). "Up-regulation of miR-10a increased ROS, TNF-α, IL-6, and MPO, and downregulation reduced sepsis-induced liver injury." (PMID 34956235, 2021). "Whole blood from patients with simple sepsis showed a higher expression of TREM-1 and higher levels of IL-6, IL-8, IL-10 and TNF-α upon stimulation with LPS when compared with whole blood from patients with severe sepsis." (PMID 33924130, 2021). "When compared to the sham-operated animals, the saline-treated septic animals showed lower OER, but higher IL-6 and organ dysfunction (ROFA) scores 24h after sepsis induction." (PMID 34475875, 2021). "In our study, IL‐6 and TNF‐α expression displayed the same profile: 2 h after sepsis induction, a sharp increase was detected, with nevertheless one exception: for TNF‐α, in non‐supplemented rats where this increase was not significant (p = 0.058)." (PMID 34288548, 2021). "We measured the pro-inflammatory cytokine levels (IL-1β, IL-6, TNF-α) in the plasma and hippocampus to evaluate central and peripheral inflammation during the acute phase of sepsis in SAMP8 and SAMR1." (PMID 33643027, 2021). "Although IL-6 is weaker than the neutrophil CD64 and PCT in the diagnosis of sepsis in adult patients, some studies have shown that it also plays a role in the prognosis of infectious diseases." (PMID 33902476, 2021). "Numerous studies demonstrated that the excessive release of proinflammatory cytokines, such as IL-1β, IL-6, and TNF-α, triggered the pathophysiological abnormities of sepsis and played prominent roles in septic AKI." (PMID 33511217, 2021). "In recent years, PCT, interleukin-6 (IL-6), HBP, C-reactive protein (CRP), serum resistin, and other indicators have been used clinically to assess the severity and prognosis of sepsis." (PMID 34514164, 2021). "IL-6 usually increases earlier than that of CRP and PCT, making it a potential biomarker for early detection of sepsis." (PMID 34630395, 2021). "To determine if gestational sepsis induces upregulation of cytokine up in neonates, we analyzed the levels of TNF-α, IL-1β, and IL-6 in the liver, lung, and brain of neonates at P2 and P8." (PMID 33632243, 2021).
Sepsis (continued). "In a zinc supplementation RCT of neonates with clinical sepsis in India, zinc supplementation was found to reduce concentrations of serum TNF-α and IL-6." (PMID 34836049, 2021). "Debate surrounds the possible increased infectious risks associated with therapies like IL-6- or IL-6R-targeted agents; however, findings from these ongoing studies will expand the understanding of potential clinical applications of IL-6 pathway inhibition to non-Covid-19 sepsis as well." (PMID 33803628, 2021). "Novel biomarkers for sepsis are required because the existing inflammatory biomarkers for its diagnosis, such as C reactive protein (CRP), procalcitonin (PCT), and interleukin (IL)-6, have respective shortcomings in identification of sepsis onset." (PMID 34055659, 2021). "The scores for WBC, CRP, SAA, IL-6, APACHE II, and SOFA in the sepsis group were all higher than those in the infection group, with statistical significance (p < 0.05)." (PMID 34745113, 2021). "The HBP level (AUC 0.85) had the highest predictive power for identifying children who developed severe sepsis, followed by D-dimer (AUC 0.80), PCT (AUC 0.80), IL-6 (AUC 0.74), and N% (AUC 0.72)." (PMID 34778149, 2021). "The increase in plasma levels of inflammatory cytokines, such as IL-6 or TNF-α, is proportional to the severity of sepsis, and correlates with mortality." (PMID 33946773, 2021). "It is of great value for the treatment of sepsis to explore the deep meaning and hidden important clinical information of NLR plus IL-6." (PMID 33796105, 2021). "The predictive ability to identify children who progressed to sepsis was significantly moderate for PCT (AUC 0.82), D-dimer (AUC 0.80), CRP (AUC 0.80), and IL-6 (AUC 0.74) and was significantly mild for N% (AUC 0.68) and HBP (AUC 0.67)." (PMID 34778149, 2021). "To date, numerous biomarkers such as interleukin-6 (IL-6), C-reactive protein (CRP), and procalcitonin (PCT), have been used for the early detection of sepsis." (PMID 34442376, 2021). "Main Outcome(s) and Measure(s): The primary outcome was IL-6 plasma concentration in MIS-C and sepsis group at admission to the intensive care unit." (PMID 34869111, 2021). "In another study conducted in an emergency department, which included patients older than age 65 years, the CRP and erythrocyte sedimentation rate were more reliable markers for differentiating sepsis from SIRS compared with PCT, WBC, and interleukin-6 levels." (PMID 34344141, 2021). "The proinflammatory response in the acute phase of sepsis eliminates invading pathogens and involves immunocyte activation and subsequent production of cytokines such as TNF-α, IL-1β, and IL-6." (PMID 34907156, 2021). "AE prominently downregulated CXCL-1, CXCL-8, IL-6, TNF-α, Glu1, and HMGB1 mRNA expression but activated IL-1RN, IL-10, Sirt-1, and Nrf-2 mRNA expression in the lung during sepsis." (PMID 34493741, 2021). "In particular, in LPS-induced-inflammation, PL suppressed leukocytes migration, TNF-α and IL-6 production, NF-κB and regulated extracellular kinases (ERK) 1 and 2 activation, and reduced mortality in sepsis." (PMID 34831393, 2021). "Both, MVHSstatic and MVHSdynamic correlated moderate-to-strong with SOFA score, number of dysfunctional organs, lactate, CRP, IL-6 and PCT (all p < 0.001) in a pooled analysis that included healthy controls and sepsis patients." (PMID 33741036, 2021). "Sepsis also up-regulates the inflammatory cytokines TNF-α, IL-6 and HMGB1 in BV-2 microglia cultures and animals." (PMID 34711216, 2021). "Another analysis of over 1,400 pneumonia patients in the United States reported that IL-6, tumor necrosis factor (TNF), and IL-10 were elevated at intake in patients who developed severe sepsis and/or ultimately died." (PMID 33594340, 2021).